TK2 (thymidine kinase 2)
Description:
Phosphorylates thymidine, deoxycytidine, and deoxyuridine in the mitochondrial matrix. In non-replicating cells, where cytosolic dNTP synthesis is down-regulated, mtDNA synthesis depends solely on TK2 and DGUOK. Widely used as target of antiviral and chemotherapeutic agents.
Synonyms: SCA31; MTDPS2; MTTK; PEOB3; TK2-EXT
Tractability: Small molecule: a high-quality ligand is known; it belongs to a druggable protein family. PROTAC: its protein half-life has been measured; a small molecule that binds it is known.
Target class: Enzyme; Transferase
Gene: Protein-coding gene on chromosome 16 (66,508,003 to 66,552,544, reverse strand). Ensembl gene ENSG00000166548.
Subcellular location: Mitochondrion
Pathways (Reactome):
Metabolism: Pyrimidine salvage
Gene Ontology:
Molecular function: deoxycytidine kinase activity; protein binding; thymidine kinase activity; nucleoside kinase activity; ATP binding; deoxynucleoside kinase activity
Biological process: nucleobase-containing compound metabolic process; pyrimidine nucleoside salvage; deoxycytidine metabolic process; deoxyribonucleoside monophosphate biosynthetic process; nucleotide biosynthetic process; thymidine metabolic process
Cellular component: mitochondrion; cytoplasm; mitochondrial matrix
Genetic constraint (gnomAD): Loss-of-function variants: 36 observed, 43.18 expected, observed/expected ratio (o/e) 0.83, 90% interval 0.64 to 1.1. The upper end of that interval is the gene's LOEUF score, 1.1, which puts it in group 4 of 6, group 1 being the genes least tolerant of losing a copy. Missense variants: 320 observed, 349.14 expected, observed/expected ratio (o/e) 0.92, 90% interval 0.84 to 1. Synonymous variants: 128 observed, 124.07 expected, observed/expected ratio (o/e) 1.03, 90% interval 0.89 to 1.2.
Gene-disease validity (ClinGen):
ClinGen rates the evidence that TK2 causes each of these diseases.
mitochondrial disease (autosomal recessive): Definitive.
Homologues: Orthologues: chimpanzee TK2 (99% identical), macaque TK2 (94% identical), pig TK2 (82% identical), guinea pig TK2 (81% identical), mouse Tk2 (81% identical), rat Tk2 (80% identical), dog TK2 (78% identical), tropical clawed frog tk2 (57% identical), zebrafish tk2 (57% identical), Drosophila melanogaster dnk (37% identical). Paralogues in human: DCK (31% identical), DGUOK (27% identical), NDUFA10 (21% identical).
Diseases named in the same sentence as TK2 in open-access papers:
TK2 is named in the same sentence as 62 diseases in open-access papers, as found by Europe PMC text mining. Sharing a sentence is not in itself a finding about the gene and the disease. The quoted sentences say what the papers report.
mitochondrial DNA depletion syndrome (14 papers, 2012 to 2025). The mitochondrial DNA (mtDNA) depletion syndrome (MDS) is a clinically heterogeneous group of mitochondrial disorders characterized by a reduction of the mtDNA copy number in affected tissues without mutations or rearrangements in the mtDNA. "Mutations in the TK2 gene are strongly associated with mitochondrial DNA depletion syndrome (MDS), a severe condition with high mortality and poor outcomes." (PMID 40098049, 2025). "In humans, homozygous or compound heterozygous loss-of-function mutations of TK2 associated with mitochondrial DNA depletion syndrome (MDS) result in 1–39% TK2 activity relative to healthy controls and typically manifest as infantile-onset severe myopathy." (PMID 35084690, 2023). "We had only two patients who underwent NGS and found variants in other disease-related genes, one case with TK2-related mitochondrial DNA depletion syndrome, myopathic form (TK2-MDS), and one with COL4A2-associated myopathy." (PMID 38002481, 2023). "A deficiency in TK2 leads to a progressive depletion of mtDNA resulting in a so-called mitochondrial DNA depletion syndrome (MDDS) when the mtDNA drops below a significant level." (PMID 33276480, 2020). "Kalko and colleagues undertook transcriptomic analysis of muscle biopsies from patients with mitochondrial DNA depletion syndrome caused by loss of function in the thymidine kinase 2 (TK2) gene." (PMID 32310257, 2020). "Mutations in the gene encoding thymidine kinase 2 (TK2) result in the myopathic form of mitochondrial DNA depletion syndrome which is a mitochondrial encephalomyopathy presenting in children." (PMID 24484525, 2014). "To date, mutations in just four of these genes – POLG, PEO1, RRM2B and recently TK2 – have been described as causes of both infantile mtDNA depletion syndromes and adult-onset, multiple mtDNA deletion disorders." (PMID 22508010, 2012). "Thymidine kinase (TK2) deficiency causes mitochondrial DNA depletion syndrome." (PMID 36232299, 2022). "Increased lipid may be present in fibres with or without ragged red change and COX deficiency, e.g., in KSS and PEO due to mtDNA rearrangements, mtDNA depletion syndrome due to mutations in TK2, RRM2B, SUCLA2 and SUCLG1, and CoQ2." (PMID 28677615, 2017). "Thymidine kinase 2 (TK2) deficiency in humans causes mtDNA depletion syndrome." (PMID 26398948, 2015). "Defects in thymidine kinase 2 (TK2) also impact mtDNA, leading to a mtDNA depletion syndrome with progressive myopathy." (PMID 36056365, 2022). "Even late in the disease course, overtly dystrophic features with necrosis, fibrosis and fatty infiltration are not seen, with the exception of TK2-related myopathic form of mtDNA depletion syndrome." (PMID 28677615, 2017).
Mitochondrial myopathy (12 papers, 2014 to 2026). "Thymidine kinase 2 deficiency (TK2d) (MIM 609560) is an ultra-rare, autosomal recessive mitochondrial myopathy caused by TK2 variants, leading to mitochondrial DNA depletion and/or multiple deletions." (PMID 42318512, 2026). "Clinically, TK2 deficiency is characterized by a range of symptoms, including hypotonia, muscle weakness, ptosis, and exercise intolerance, which are typical of mitochondrial myopathies." (PMID 40098049, 2025). "Mice homozygous for a disease causing mutation (Tk2-/- mice) develop a mitochondrial myopathy similar to that observed in early onset human TK2 deficiency." (PMID 35668433, 2022). "An exception among mitochondrial myopathies is a TK2 deficiency, where hyperCKemia is common and typically 10-fold above the upper normal limit (up to 30-fold)." (PMID 35011763, 2021). "GDF-15, a biomarker identified in the analysis of transcriptomic profiling of TK2 deficient human skeletal muscle, has been proven useful in the diagnosis of mitochondrial myopathies, being especially increased in patients with mitochondrial TK2 deficiency." (PMID 31060578, 2019). "We focused our attention on the muscle MRI pattern of patients with TK2 deficiency as this is the only mitochondrial myopathy with a specific treatment that can change the natural history of the disease and, therefore, providing a correct diagnosis to the patients is extremely important." (PMID 35286480, 2022). "However, as in other TK2 deficiency forms, they also revealed dystrophic features which are distinct from the majority of other mitochondrial myopathies." (PMID 31060578, 2019). "Elevated CK is unusual in other forms of mitochondrial myopathies except for TK2 deficiency and therefore it may be an important hallmark of this disease." (PMID 29361167, 2018). "In addition, our study enriches the TK2 gene lineage and expands the understanding of mitochondrial myopathy caused by TK2 gene mutation, which lays a foundation for further understanding of the disease and proposing possible improved diagnosis and treatment methods in the future." (PMID 40098049, 2025). "Besides presenting as mitochondrial myopathy, TK2 mutations may also be associated with other clinical manifestations, including sensorineural hearing loss, PEO/PMM with multiple mtDNA deletions, early-onset encephalopathy, SMA-like phenotype, and multisystemic involvement." (PMID 40098049, 2025). "Autosomal recessive human thymidine kinase 2 (TK2) mutations cause TK2 deficiency, which typically manifests as a progressive and fatal mitochondrial myopathy in infants and children (note: not classified as MD)." (PMID 36471396, 2022). "We describe 18 patients with mitochondrial myopathy due to mutations in the TK2 gene with absence of clinical symptoms until the age of 12." (PMID 31060578, 2019).
lung carcinoma (5 papers, 2017 to 2022). "The expression levels of TK2 were significantly associated with prognosis in lung cancer tissues." (PMID 35941578, 2022). "Furthermore, we found that pyrimidine metabolic rate–limiting enzymes CAD, RRM2, DTYMK, TYMS, TK2, and NR5C2 were all associated with the clinical outcomes of lung cancer and liver cancer." (PMID 32638267, 2020). "However, consistent with the decreased expression levels of NR5C2 and TK2 in lung cancer tissues, patients with higher expression levels of NR5C2 and TK2 had better prognosis than patients with low expression levels of those genes." (PMID 32638267, 2020). "However, TK2 and NT5C2 were relatively downregulated in lung cancer tissues." (PMID 32638267, 2020). "However, TK2 and NT5C2 were downregulated in lung cancer tissues." (PMID 32638267, 2020).
spinocerebellar ataxia type 31 (4 papers, 2020 to 2025). "Repeats of pentapeptide microsatellites in the shared exon of brain expressed associated with NEDD4 1 (BEAN1) and thymidylate kinase 2 (TK2) are responsible for spinocerebellar ataxia type 31 (SCA31)." (PMID 32951567, 2021). "Spinocerebellar ataxia type 31 (SCA31), an autosomal-dominant neurodegenerative disorder characterized by progressive cerebellar ataxia with Purkinje cell degeneration, is caused by a heterozygous 2.5–3.8 kilobase penta-nucleotide repeat of (TTCCA)n in intron 11 of the thymidine kinase 2 (TK2) gene." (PMID 35084690, 2023). "Spinocerebellar ataxia type 31 (SCA31) is a neurological disease caused by insertion of a 2.5 to 3.8 kb repeat that includes the long TGGAA stretch present in a common intronic region of BEAN1 (brain expressed associated with NEDD4-1) and thymidine kinase 2 (TK2) genes." (PMID 32093161, 2020).
breast carcinoma (3 papers, 1988 to 2019). "Serum TK from 20 patients with breast cancer and 19 control patients was further assayed to ascertain the relative contributions of the thymidine kinase isozymes TK1 and TK2 to total TK levels." (PMID 3408646, 1988).
MELAS (3 papers, 2014 to 2022). "Highest levels of GDF-15 were present in the serum of patients with thymidine kinase 2 (TK2) defects, MELAS, defects in MT-TL1 encoding mitochondrial tRNA leucine, and patients with Pearson syndrome and KSS." (PMID 36361969, 2022). "Amongst patients with the highest levels of GDF-15 were children with mutations in TK2, patients with MELAS and the common mutations in the MT-TL1 gene and patients with deletions in mtDNA including one patient with Pearson Syndrome and two patients with KSS." (PMID 26867126, 2016). "We observed TUNEL positivity in myonuclei and apoptotic bodies in TK2 deficient muscle as well as in some of the myonuclei of the RRF in a patient with a MELAS phenotype (P12)." (PMID 24484525, 2014).
mitochondrial DNA depletion syndrome 2 (3 papers, 2021 to 2024). "The TK2 gene, linked to mitochondrial DNA depletion syndrome 2 (MTDPS2), usually presents as myopathy but can vary widely in clinical presentation." (PMID 39457470, 2024). "Myopathic MDS, also known as mitochondrial DNA depletion syndrome 2 (MTDPS2) or TK2 deficiency, is characterized by the reduction of mtDNA content in the affected tissues." (PMID 35237671, 2021). "Variants in the TK2 gene, associated with mitochondrial DNA depletion syndrome 2 (OMIM#609560), and in the MBP gene, associated with susceptibility to multiple sclerosis (OMIM#126200), were also found." (PMID 33815474, 2021).
respiratory failure (3 papers, 2020 to 2022). The significant impairment of gas exchange within the lungs resulting in hypoxia, hypercarbia, or both, to the extent that organ tissue perfusion is severely compromised. "In patients affected by TK2 deficiency the main reported symptom is myopathy with progressive muscle weakness leading to respiratory failure." (PMID 35767531, 2022). "Our goal was to analyze postmortem tissues of an adult patient with late-onset thymidine kinase 2 (TK2) deficiency who died of respiratory failure." (PMID 34070501, 2021). "Here we report, for the first time to our knowledge, the autopsy results of an adult patient with late-onset TK2 deficiency who died of respiratory failure at the age of 43." (PMID 34070501, 2021). "Respiratory failure is the main cause of death in patients of all ages with TK2 deficiency." (PMID 34070501, 2021). "For example, TK2-induced mtDNA depletion usually presents before the age of two years with myopathy, feeding difficulty, hypotonia, and within a few years respiratory failure." (PMID 33426505, 2020).
Respiratory insufficiency (3 papers, 2019 to 2026). "People with thymidine kinase 2 deficiency experience progressive myopathy, bulbar weakness and respiratory insufficiency, often losing the ability to walk, eat and breathe independently." (PMID 42318512, 2026). "Patients with late onset TK2 deficiency have a consistent and recognizable clinical phenotype and a poor prognosis, due to the high risk of early and progressive respiratory insufficiency." (PMID 31060578, 2019). "Most of the patients with TK2 mutations have an infantile onset form, presenting at or soon after birth with generalized weakness, respiratory insufficiency, and death at 1 to 3 years of age." (PMID 31718067, 2019).
cardiomyopathy (2 papers, 2025). A disease of the heart muscle or myocardium proper. "In order to figure out the impact of TK2 on the cardiac phenotype, the cardiomyocyte or the heart-specific Cre mouse models are needed to further elucidate the mechanisms underlying cardiomyopathy caused by TK2 mutations." (PMID 40556660, 2025). "Nuclear gene defects in mtDNA maintenance, such as mutations in TK2 and POLG, can result in mtDNA depletion or multiple deletions, undermining respiratory chain integrity and precipitating severe early-onset cardiomyopathy." (PMID 41301490, 2025).
Encephalopathy (2 papers, 2014 to 2025). Encephalopathy is a term that means brain disease, damage, or malfunction. "Therefore, intrathecal treatment may be required in the Tk2−/− mice and TK2 patients with encephalopathy." (PMID 24968719, 2014).
External ophthalmoplegia (2 papers, 2019 to 2020). Paralysis of the external ocular muscles. "Thymidine kinase 2 (TK2) deficiency may determinate a late onset case of mild chronic progressive external ophthalmoplegia (CPEO)." (PMID 33383961, 2020).
mitochondrial encephalomyopathy (2 papers, 2014 to 2025). A heterogenous group of disorders characterized by alterations of mitochondrial metabolism that result in muscle and nervous system dysfunction. "We investigated caspase-3 activation at the protein level by immunofluorescence in the muscle biopsies of 3 patients with TK2 mutations (P3, P4 and P11) and other mitochondrial encephalomyopathies (P7 and P12)." (PMID 24484525, 2014). "Caspase-3 activation leads to DNA fragmentation so we performed the TUNEL assay in muscle biopsies from patients with TK2 mutations (P3, P4), a patient with SUCLA2 mutations (P10) and patients with confirmed mitochondrial encephalomyopathy (P6, P7 and P12)." (PMID 24484525, 2014).
Adult onset (1 paper, 2025). Onset of disease manifestations in adulthood, defined here as at the age of 16 years or later. "Recessive variants in the TK2 gene cause thymidine kinase 2 deficiency (TK2d) presenting with infantile, childhood, or adult-onset myopathy." (PMID 40030095, 2025).
AIDS (1 paper, 2013). A syndrome resulting from the acquired deficiency of cellular immunity caused by the human immunodeficiency virus (HIV). "Our results show that, compared with the control group, the concentration of TK2 protein was 2.2-fold higher in the group of children with AIDS treated for 36 to 72 months, suggesting that TK2 induction in the PBMCs of children with AIDS is associated with long-term HAART." (PMID 23468942, 2013). "TK2 levels were 3-fold higher in the group of children with AIDS treated for less than 36 months as compared with control PBMCs." (PMID 23468942, 2013). "However, in the group of children with AIDS treated for 36 to 72 months, TK2 mRNA levels were significantly induced." (PMID 23468942, 2013).
cerebellar ataxia (1 paper, 2023). A neurological syndrome characterized by clumsy and uncoordinated movement of the limbs, trunk, and cranial muscles. "Furthermore, tk2 knockout mice show remarkable cerebellar ataxia with Purkinje cell degeneration." (PMID 35084690, 2023).
delirium (1 paper, 2025). A disorder characterized by confusion; inattentiveness; disorientation; illusions; hallucinations; agitation; and in some instances autonomic nervous system overactivity. "Our findings show that higher expression of 8 genes, includingDHODH,DHRS7B,TOP1MT,CASP8,GFM1,CPT1B,TK2, andGPD2, could decrease the risk of delirium." (PMID 41330563, 2025). "There were eight protective genes (DHODH,DHRS7B,TOP1MT,CASP8,GFM1,CPT1B,TK2,GPD2), and four genes (SCP2,DMPK,GSTK1,SIRT3) that increased delirium risk, as shown inFigure 2, withp = 0.05 (dotted line); and false discovery rate (FDR) < 0.05 (red asterisks)." (PMID 41330563, 2025).
encephalomyopathy (1 paper, 2013). "The TK2−/− mouse model displays symptoms similar to humans harboring TK2 deficient infantile fatal encephalomyopathy." (PMID 23505564, 2013). "This study provides insight into the mechanism of encephalomyopathy caused by TK2 deficiency-induced mtDNA depletion that may be used to explore novel therapeutic strategies." (PMID 23505564, 2013). "Humans carrying TK2 deficiency primarily present with severe myopathy and display neurological phenotypes whereas DGUOK, POLG and MPV17 deficiencies have been associated with liver failure and encephalomyopathy." (PMID 23505564, 2013).
epilepsy (1 paper, 2014). A brain disorder characterized by episodes of abnormally increased neuronal discharge resulting in transient episodes of sensory or motor neurological dysfunction, or psychic dysfunction. "The highest levels were detected in two patients with POLG mutations (85252 pg/mL and 13215 pg/mL) followed by P4 of this study carrying TK2 mutations (8000 pg/mL) and a patient with lactic acidosis and epilepsy bearing the mtDNA A3243G mutation (P12), (6999 pg/mL)." (PMID 24484525, 2014).
Facioscapulohumeral dystrophy (1 paper, 2023). Facioscapulohumeral muscular dystrophy (FSHD) is characterized by progressive muscle weakness with focal involvement of the facial, shoulder and limb muscles. "Generally speaking, later-onset forms of TK2 deficiency can mimic a wide spectrum of neuromuscular disorders, including facioscapulohumeral dystrophy (FSHD), oculopharyngeal muscular dystrophy (OPMD), LOPD, and even SMA type 3." (PMID 37239314, 2023).
hypertrophic cardiomyopathy (1 paper, 2018). A condition in which the myocardium is hypertrophied without an obvious cause. "Recently, the phenotypic spectrum of TK2 mutations has been extended by the description of a female TK2 carrier manifesting with lethal hypertrophic cardiomyopathy." (PMID 29988795, 2018).
limb-girdle muscular dystrophy (1 paper, 2020). Limb-girdle muscular dystrophy (LGMD) is a heterogeneous group of muscular dystrophies characterized by proximal weakness affecting the pelvic and shoulder girdles. "Clinically, TK2 mutations manifest with infantile-onset myopathy, predominantly affecting the proximal limb muscles (Duchenne-like, or limb-girdle muscular dystrophy (LGMD)-like presentations) and progressing to muscular respiratory failure due to involvement of the respiratory muscles." (PMID 32316520, 2020).